NALT1 (NOTCH1 associated lncRNA in T cell acute lymphoblastic leukemia 1)
Synonyms: TCONS_l2_00029132; LINC01573; MIR4674HG; NALT
Gene: Long non-coding RNA gene on chromosome 9 (136,546,162 to 136,552,541, forward strand). Ensembl gene ENSG00000237886.
Diseases named in the same sentence as NALT1 in open-access papers:
NALT1 is named in the same sentence as 13 diseases in open-access papers, as found by Europe PMC text mining. Sharing a sentence is not in itself a finding about the gene and the disease. The quoted sentences say what the papers report.
gastric cancer (3 papers, 2022 to 2024). A primary or metastatic malignant neoplasm involving the stomach. "LncRNA NOTCH1 associated lncRNA in T cell acute lymphoblastic leukemia 1 (NALT1) acts as a regulator to be implicated in the development of gastric cancer (GC)." (PMID 36385135, 2022). "NALT1 has been implicated in the occurrence of gastric cancer (GC)." (PMID 36385135, 2022). "In another study, NALT1 was significantly overexpressed in gastric cancer tissues and cells, and this overexpression was closely associated with tumor invasion, metastasis, and poor prognosis in gastric cancer patients." (PMID 38568288, 2024). "Recently, a similar role of NALT1 was reported in gastric cancer (GC), where the knockdown of this lncRNA resulted in a decrease in NOTCH1 expression, which reduced the invasion and migration of GC cells." (PMID 37628760, 2023).
colorectal tumors (1 paper, 2022). "Hence, NALT1/miRNA-574-5p/PEG10 axis might be a promising strategy for the diagnosis and treatment of colorectal tumors." (PMID 36385135, 2022).
hepatocellular carcinoma (1 paper, 2024). A malignant tumor that arises from hepatocytes. "Similar to the reported roles of NALT1 in various cancers, apart from our CRC findings, dysregulation of LINC02499 was detected in a hepatocellular cancer (HCC)." (PMID 38568288, 2024).
pancreatic carcinoma (1 paper, 2023). "For example, the upregulation of lncRNAs DCST1-AS1, NALT1, LBX2-AS1, and MACC1-AS1 correlates with the poor survival of patients with EC, GC, NSCLC, and pancreatic carcinoma, respectively." (PMID 37628760, 2023).
rectum adenocarcinoma (1 paper, 2022). An adenocarcinoma arising from the rectum. "Also, an obvious positive correlation was observed between NALT1 and PEG10 in patients with rectum adenocarcinoma by the GEPIA database." (PMID 36385135, 2022).
cancer (2 papers, 2022 to 2024). A tumor composed of atypical neoplastic, often pleomorphic cells that invade other tissues. "In our study, high-throughput RNA sequencing results supported the findings of the referenced studies, showing higher levels of NALT1 in cancer patients, specifically in sEVs isolated from peripheral blood of individuals with CRC." (PMID 38568288, 2024). "In their study, NALT1 contributed to cancer progression by acting as a molecular sponge for microRNA-574-5p." (PMID 38568288, 2024). "It was observed that high expression of NALT1 was markedly correlated with advanced cancer stage in the clinic." (PMID 36385135, 2022). "Additionally, dysregulated NALT1 expression was found to be associated with overall survival (OS) in stomach adenocarcinoma (STAD) and might facilitate cancer cell proliferation." (PMID 36385135, 2022).
tumor (2 papers, 2022 to 2024). "We found that knockdown of NALT1 decreased tumor volume and inhibited tumor growth compared with the control group." (PMID 36385135, 2022). "Meanwhile, overexpression of NALT1 significantly promoted tumor growth compared with the control group." (PMID 36385135, 2022). "Multivariate regression revealed that high level of NALT1 was related to differentiation (p < 0.001), distant metastasis (p = 0.0085), and tumor size (p = 0.0069)." (PMID 36385135, 2022). "Interestingly, our results showed that PEG10 expression was closely related to the CRC tumor stage and survival, as well as positively correlated with NALT1 levels in CRC tissue." (PMID 36385135, 2022). "In this study, miRNA-574-5p downregulation partially restored the effects of NALT1 on CRC cell proliferation, tumor growth, and migration." (PMID 36385135, 2022). "Furthermore, PEG10 knockdown or overexpression partially rescued the effects of miRNA-574-5p and NALT1 on CRC cell proliferation, tumor growth, and migration, suggesting that PEG10 is essential for the NALT1/miRNA-574-5p-mediated biological effects in CRC cells." (PMID 36385135, 2022).
NALT1 also shares sentences with these, for which no sentence is quoted: T cell acute lymphoblastic leukaemia (2 papers); acute lymphoblastic leukemia (1); colorectal cancer (1); infection (1); leukemia (1); uremia (1).